DUSP9 (dual specificity phosphatase 9)
Diseases named in the same sentence as DUSP9 in open-access papers (continued):
Sharing a sentence is not in itself a finding about the gene and the disease.
metabolic syndrome (1 paper, 2021). A cluster of metabolic risk factors for CARDIOVASCULAR DISEASES and TYPE 2 DIABETES MELLITUS. "This remarkable result suggests that a therapeutic approach aiming at keeping DUSP9 in an active state may be beneficial for the treatment of patients with metabolic syndrome or tumor." (PMID 34768967, 2021).
ovarian tumors (1 paper, 2025). "Notably, DUSP9 significantly upregulated SCD—a key lipogenic enzyme and known metabolic vulnerability in multiple cancers, including breast and ovarian tumors." (PMID 41383134, 2025).
pancreatic tumors (1 paper, 2008). "We also noticed increased expression of some X-linked genes related to signal transduction such as Rsk4, Dusp9 and S100g, which have not been reported previously in pancreatic tumors." (PMID 18218118, 2008).
prediabetes (1 paper, 2023). "In summary, we found significant associations between prediabetes risk and five variants closely related to the FTO, HNF4A, WFS1, DUSP9, and ZFAND6 genes (rs4812829, rs1801214, rs5945326, rs11642841, and rs11634397) among Saudi Arabian adults." (PMID 36980809, 2023). "The current study revealed that their variants, including the GA heterozygous of DUSP9 (rs5945326) and GG heterozygous of ZFAND6 (rs11634397) genotypes, contributed to decreased risk of developing prediabetes." (PMID 36980809, 2023). "Furthermore, heterozygous GA of rs4812829 (HNF4A), rs5945326 (DUSP9), and rs11634397 (ZFAND6), along with heterozygous TC of rs1801214 (WFS1), were associated with a decreased risk for prediabetes." (PMID 36980809, 2023).
preeclampsia (1 paper, 2022). Preeclampsia is a hypertensive disorder of pregnancy that is characterized by new-onset hypertension with proteinuria presenting after 20 weeks of gestation, and depending on mild or severe forms may initially present with severe headache, visual disturbances, and hyperreflexia. "Moreover, DUSP9 was reported to be associated with pregnancy complications, such as gestational diabetes mellitus and preeclampsia." (PMID 35163786, 2022). "Note that DUSP9 was obviously expressed in villous trophoblast, along with its downregulation in placenta across human gestation and in severe preeclampsia." (PMID 35163786, 2022).
soft tissue sarcoma (1 paper, 2024). A malignant neoplasm arising from muscle tissue, adipose tissue, blood vessels, fibrous tissue, or other supportive tissues excluding the bones. "We further established two hub genes (DUSP9 and TNFSF14) prognosis markers and risk scores associated with soft tissue sarcoma prognosis and immune therapy response." (PMID 38720884, 2024). "DUSP9 functions differently in different types of cancer and has not been reported in soft tissue sarcoma." (PMID 38720884, 2024).
tumor (16 papers, 2011 to 2025). "Functional enrichment analysis revealed that the DUSP9-correlated gene network was implicated in cell adhesion, transcription, wound healing and cell migration, which suggested a mechanism for tumor progression." (PMID 40861803, 2025). "In our study, the results of univariate Cox regression analysis showed that tumor size, T stage, N stage, metastasis, Fuhrman grade and DUSP-9 expression were significantly associated with overall survival." (PMID 21943117, 2011). "Because Erk pathway activation plays a key role in tumor growth and metastasis, we hypothesized that the oncogenic phenotype induced by DUSP9 silencing may be associated with activation of the Erk pathway." (PMID 33072575, 2020). "Further statistical analysis revealed that low DUSP9 expression level in CRC was closely associated with tumor size, depth of invasion, and advanced TNM stage, indicating that DUSP9 may be involved in the progression of CRC." (PMID 33072575, 2020). "In addition, decreased DUSP9 level was closely associated with larger tumors, deeper invasion, and advanced cancer stage, indicating that DUSP9 down-regulation is associated with tumor progression and poor prognosis in CRC." (PMID 34768967, 2021). "Moreover, low DUSP9 protein expression in CRC was closely associated with tumor size, depth of invasion, and advanced TNM stage, indicating that DUSP9 may be involved in the progression of CRC." (PMID 33072575, 2020). "The expression of DUSP9 escalated with advancing tumor grade and stage, emerging as an independent prognostic factor associated with poor outcomes in HNSCC." (PMID 40861803, 2025). "Both tumor cell function experiments and related gene enrichment analysis were suggested that DUSP9 contributed to tumor progression, promoting tumor cell proliferation and migration." (PMID 40861803, 2025). "Given the complexity of HNSCC tumor subtypes, we grouped the samples based on the tumor tissue source and visualized for DUSP9 expression." (PMID 40861803, 2025). "DUSP9 negatively regulates PD-L1 expression in multiple tumor cells, and mechanistically, DUSP9 dephosphorylates STAT3 to mediate the inhibitory role." (PMID 41405398, 2025). "Using limiting dilution tumourigenicity assays, we showed that DUSP9 knockdown significantly increased the minimal cell number required for tumour initiation in vivo." (PMID 41383134, 2025). "IHC staining of a tissue microarray comprising 63 paired HCC and adjacent tissue samples also demonstrated robust DUSP9 expression in HCC tumours." (PMID 41383134, 2025). "Immunohistochemical analysis of DUSP9 staining in tumor tissues from 48 HNSCC patients confirmed significantly increased DUSP9 expression in tumor tissues compared to paratumor tissues." (PMID 40861803, 2025). "At the protein level, proteomic analysis of 165 paired HCC and adjacent tissues from the CPTAC dataset confirmed that DUSP9 protein was significantly overexpressed in tumour tissues." (PMID 41383134, 2025). "The dot plot also showed the absolute predominant expression of DUSP9 in tumor epithelial cells, in addition, the new finding was that DUSP9 was higher expressed in metastatic tissues than primary tumors." (PMID 40861803, 2025). "ScRNA-seq data analysis suggested that DUSP9 was selectively expressed in tumor cells, with negligible expression in immune cells and stromal cells, and showed an elevated trend from primary tissues to metastatic tissues." (PMID 40861803, 2025). "In syngeneic tumor models, the combination of DUSP9 targeting and PD-1 antibody can enhance therapeutic sensitivity." (PMID 41405398, 2025). "In clinical tissue specimens, DUSP9 expression was significantly higher in HCC tumours compared to adjacent non‐tumour tissues." (PMID 41383134, 2025). "Conversely, DUSP9‐knockdown MHCC‐97H xenografts showed reduced triglyceride content compared to control tumours." (PMID 41383134, 2025).
tumor (continued). "The scRNA-seq analysis further demonstrated that DUSP9 expression was confined to tumor epithelial cells, with minimal expression in fibroblasts, endothelial cells or immune cells." (PMID 40861803, 2025). "We further examined DUSP9 protein expression in clinical samples, including primary tumor and matched paratumor tissues." (PMID 40861803, 2025). "Consistent findings were observed in the TCGA‐LIHC and CHCC cohorts, where high DUSP9 expression was associated with adverse clinicopathological features, including high serum AFP and poor tumour differentiation." (PMID 41383134, 2025). "To further elucidate the molecular mechanisms underlying DUSP9‐induced stemness, we performed Western blot on xenograft tumours derived from DUSP9‐modulated HCC cells." (PMID 41383134, 2025). "Western blot analysis of eight randomly selected paired HCC and adjacent tissues confirmed that DUSP9 was highly expressed in tumour tissues, with low expression in adjacent tissues." (PMID 41383134, 2025). "According to the public data, DUSP9 was significantly up-regulated in HNSCC tumor tissues compared to normal tissues, confirmed by clinical data and single-cell RNA sequencing (scRNA-seq) data." (PMID 40861803, 2025). "DUSP9‐overexpressing tumours showed higher levels of DUSP9, SCD, NANOG and Ki67, whereas DUSP9‐knockdown tumours displayed reduced expression of these markers." (PMID 41383134, 2025). "DUSP9 deficiency inhibited the proliferation and migration of HNSCC cells, while DUSP9 overexpression increased their proliferative and migratory abilities, further supporting the phenotype of promoting tumor growth and metastasis of DUSP9 in HNSCC." (PMID 40861803, 2025). "Representative IHC images showed that poorly differentiated tumours exhibited higher DUSP9 expression." (PMID 41383134, 2025). "The immunohistochemical results showed that TNFSF14 was positively expressed in the cytoplasm, DUSP9 was positively expressed in the nucleus of tumor cells, and brown-yellow staining was considered positive." (PMID 38720884, 2024). "As expected, the staining of primary tumor tissue and lung metastases showed that TNFSF14 was positively expressed as a prognostic protective factor, and DUSP9 was negatively expressed as a prognostic risk factor." (PMID 38720884, 2024). "The decrease in pERK1/2 levels mediated by DUSP9 affects the stem cell-like characteristics of triple-negative breast tumors, promoting tumor cell growth." (PMID 38720884, 2024). "In 2020, a new study reported the decreased expression of DUSP9 mRNA in approximately 81% of tumor tissues and most ccRCC cell lines." (PMID 34768967, 2021). "Altogether, these data demonstrate that DUSP9 acts as a tumor suppressor in GC cells in a JNK pathway-dependent manner." (PMID 34768967, 2021). "Functional study revealed that DUSP9 inhibited tumor migration, invasion, and metastasis both in vitro and in vivo." (PMID 33072575, 2020). "In this study, we found that Erk signaling activation was involved in the tumor progression mediated by DUSP9 silencing." (PMID 33072575, 2020). "In order to further verify the tumorigenicity of DUSP9 in vivo, we constructed a tumor model of nude mice using SW480 and LoVo CRC cell lines with stable overexpression or knockdown of DUSP9." (PMID 33072575, 2020). "In contrast, the tumor growth rate was slower, and the average tumor weight was significantly reduced in mice inoculated with LoVo cells with stable DUSP9 overexpression at the fourth week when compared with control mice." (PMID 33072575, 2020). "Transcriptome profiling studies revealed that Erk signaling was involved in the tumor progression mediated by DUSP9 silencing, which is confirmed by cell experiments and clinical tissue sample staining analysis." (PMID 33072575, 2020). "Expression of both DUSP7 and DUSP9 protein has been detected in NB tumor samples, although, in the case of DUSP9, with a low frequency." (PMID 30866462, 2019).
tumor (continued). "Our results indicate the role of DUSP-9 as a prognostic factor and a potential tumor suppressor in primary ccRCC." (PMID 21943117, 2011). "Reconstitution of DUSP-9 expression in malignant tumor cells induces cell death and tumor suppression." (PMID 21943117, 2011). "Overall, 117 of the 211 tumor samples showed low expression of DUSP-9(score ≤4), whereas 94 samples showed high expression (score ≥5)." (PMID 21943117, 2011). "The DUSP-9 protein expression in the 102 tumor tissue samples was lower than that in the adjacent normal tissue samples (p < 0.001, paired-sample t test)." (PMID 21943117, 2011). "The decreased expression of DUSP-9 was correlated with gender, pathologic stage, Fuhrman grade, tumor size, recurrence, TNM stage, and prognosis." (PMID 21943117, 2011). "The transcription level of DUSP-9 was determined by quantitative RT-PCR assays of 46 ccRCC tumor samples and the paired adjacent normal tissue samples." (PMID 21943117, 2011). "In 45 tumor samples, the mRNA level of DUSP-9 was significantly lower than that in the adjacent normal tissue sample (p < 0.001, paired-sample t tests)." (PMID 21943117, 2011). "Immune infiltration analysis in HNSCC using the TIMER database highlighted a negative association between DUSP9 expression in tumor tissues and the extent of immune cell infiltration, particularly CD8+ T cells, neutrophils, and dendritic cells." (PMID 40861803, 2025). "Furthermore, DUSP9 expression in tumor tissues exhibited an inverse relationship with immune cell infiltration within the tumor microenvironment (TME)." (PMID 40861803, 2025). "We also analyzed the various clinical features contributing to DUSP9 expression in tumor tissues." (PMID 40861803, 2025). "Therefore, it is plausible that DUSP9 promotes the development of head and neck tumors through dual effects on malignant cells and tumor microenvironment." (PMID 40861803, 2025). "The results showed the mRNA expression level of DUSP9 was significantly elevated in tumor tissues." (PMID 40861803, 2025). "In conclusion, our study demonstrates that DUSP9 is up-regulated in human HNSCC and promotes tumor progression, suggested that DUSP9 may serve as a biomarker for HNSCC prognosis and a potential target for HNSCC treatment." (PMID 40861803, 2025). "DUSP9 also plays a role in regulating the tumor immune microenvironment." (PMID 40861803, 2025). "Further analysis indicated that DUSP9 expression increased with tumor grade progression." (PMID 40861803, 2025). "This selective expression pattern in tumor cells suggests that DUSP9 could be a promising therapeutic target in HNSCC." (PMID 40861803, 2025). "Consistent with mRNA findings, DUSP9 protein expression was also up-regulated in tumor samples." (PMID 40861803, 2025). "Tumour epithelial cells were further reclustered into two distinct subclusters (Subcluster 1 and Subcluster 2), and DUSP9 was predominantly expressed in Subcluster 1, which was enriched with other oncofetal and stemness‐related genes such as AFP, GPC3, IGF2, ANPEP and EPCAM." (PMID 41383134, 2025). "Inversely, knockdown of DUSP9 promoted tumor development and expansion in mice." (PMID 34768967, 2021). "Finally, grafted DUSP9-KO Hep3B cells were unable to form a tumor in comparison with parental cells." (PMID 34768967, 2021). "Together, these data supported the hypothesis that DUSP9 exerts a tumor suppressive role in HCC by inactivating the ERK pathway and lowering the level of the ERK targets MYC and Cyclin D1." (PMID 34768967, 2021). "Consequently, tumor volume and mass were significantly smaller compared to cells expressing basal or low level of DUSP9." (PMID 34768967, 2021). "Moreover, activation of the Erk signaling is involved in the DUSP9 silencing-mediated tumor growth of CRC." (PMID 33072575, 2020). "Moreover, enhanced expression of DUSP9 in malignant tumor cells led to microtubule disruption, cell death, and tumor inhibition." (PMID 33072575, 2020).
tumor (continued). "Moreover, a significant negative correlation (r = −0.642, P < 0.01) between the mRNA expression of miR-1246 and DUSP9 was found in tumor tissues from 30 CRC patients." (PMID 33072575, 2020). "It has been reported that DUSP9 could affect cell proliferation and participated in the regulation of tumor progression." (PMID 33072575, 2020). "DUSP9 was significantly downregulated in tumor tissues compared with peritumor tissues." (PMID 33072575, 2020). "Moreover, in a mouse model, DUSP9 has also been found to play an anti-tumor role in SCC and non-small cell lung cancer (NSCLC)." (PMID 33072575, 2020). "This suggests that DUSP9 knockdown can activate tumor growth and metastasis-related pathways." (PMID 33072575, 2020). "In addition, key stemness markers, including NANOG, OCT4 and SOX2, were markedly upregulated in DUSP9‐overexpressing tumours, whereas their expression was significantly reduced in DUSP9‐knockdown tumours, further supporting the role of DUSP9 in promoting stemness." (PMID 41383134, 2025). "Consequently, DUSP9 emerges as a promising target for enhancing treatment response in combination with PD-1 antibody, and functions as a potential marker for predicting the efficacy of tumor immunotherapy." (PMID 41405398, 2025). "Moreover, there was a significant correlation between the DUSP-9 expression in ccRCCs and gender (p = 0.031), tumor size (p = 0.001), pathologic stage (p = 0.001), Fuhrman grade (p = 0.002), T stage (p = 0.001), N classification (p = 0.012), metastasis (p = 0.005), and recurrence (p < 0.001)." (PMID 21943117, 2011). "Normalized against adjacent non‐tumour tissues (mean expression = 1), DUSP9 was upregulated in 52.1% of 2048 HCC tumours, whereas only 5.8% of tumours showed downregulation." (PMID 41383134, 2025). "High DUSP9 expression was positively correlated with elevated serum AFP levels, large tumour size and poorer differentiation in our HCC tissue microarray cohort." (PMID 41383134, 2025). "Quantitative analysis demonstrated significant positive correlation between DUSP9 and SCD protein expression in HCC tumours." (PMID 41383134, 2025). "Among the top 100 deregulated genes, Wnt-associated genes such as LGR5, DKK1, and NKD1, as well as the HB-related genes DUSP9, DLK1, PEG3, PEG10, IGF2BP1, and IGF2BP2 were consistently upregulated in tumor samples." (PMID 40968384, 2025). "To explore the clinical significance of DUSP9 in HNSCC, we analyzed the relative expression of DUSP9 in HNSCC patients from TCGA data source, which currently comprises 522 tumor samples and 44 normal or paratumor samples." (PMID 40861803, 2025). "DUSP9 and TNFSF14 can affect the recruitment and activation of T, B, dendritic cells, and other immune cells by changing the signaling pathways in the tumor milieu, thus affecting the efficacy of immunotherapeutic agents." (PMID 38720884, 2024). "Tumor cells from patient #4001 were characterized by overexpression of AFP, GPC3, DUSP9, DLK1, GLUL, and AXIN2, a marker of Wnt/β-catenin pathway activation." (PMID 37932266, 2023). "Concerning the mechanism, the blockade of miR-1233-3p function by the circular RNA has_circ_0004050 stimulated DUSP9 expression in A549 cells leading to ERK/JNK pathway inactivation and tumor inhibition." (PMID 34768967, 2021). "Upregulation of tumor signatures, such as GPC3, DUSP9, and CTNNB1 can be observed in tumor cells and PDX." (PMID 34497364, 2021). "In the present study, we systematically investigated the functional role of DUSP9 in CRC and found that DUSP9 was significantly downregulated in tumor tissues compared with peritumor tissues." (PMID 33072575, 2020). "However, DUSP9 knockdown in MHCC‐97H cells (MHCC‐97H‐shDUSP9) reduced tumourigenicity, with delayed tumour formation, smaller tumour size and lower tumour incidence compared to the control group (MHCC‐97H‐shNC)." (PMID 41383134, 2025).
tumor (continued). "Collectively, these integrated multi‐omic analyses identify DUSP9 as a key oncofetal protein in HCC, characterized by its elevated expression in fetal and tumour tissues, its correlation with dedifferentiation and stemness and its co‐expression with other canonical oncofetal genes." (PMID 41383134, 2025). "DUSP9 silencing activated ERK signaling and promoted tumor development." (PMID 34768967, 2021). "Histological analysis showed that tumors resulting from DUSP9-transduced cells did not express DUSP9, suggesting that engrafted cells at the origin of the tumor were likely not infected." (PMID 34768967, 2021). "The mRNA level of DUSP-9, which was determined by real-time RT-PCR, was found to be significantly lower in tumorous tissues than in the adjacent non-tumorous tissues (p < 0.001)." (PMID 21943117, 2011). "Furthermore, the interaction of DUSP9 and TNFSF14 with STS immune microenvironment may be key to tumor escape." (PMID 38720884, 2024).